IL6 (interleukin 6)
Diseases named in the same sentence as IL6 in open-access papers (continued):
Sharing a sentence is not in itself a finding about the gene and the disease.
colitis (continued). "Mice with colitis, regardless of diet, presented higher concentrations of all measured cytokines (TNF, IL-6, IL-4, IL-10, IFNy), and MCP-1/CCL2." (PMID 22073943, 2011). "Thyme essential oil, mainly constituted by p-cymene and thymol, only at high concentrations (5,000 mg/L) significantly inhibited total mRNA IL-1β expression in the mouse colon in which colitis was induced by TNBS, not inhibiting significantly IL-6 expression." (PMID 21160452, 2010). "These symbionts were exclusively enriched in the control group in our study, where they exhibited strong negative correlations with pro-inflammatory cytokines (IL-6, TNF-α) and inflammation-related genes (Lcn2, Mmp3), suggesting their protective role in mitigating colitis severity." (PMID 40356657, 2025). "Finally, note that the TNBS colitis model also showed strong negative correlations between SAA and Il6 in females and Vegfa or Nos2 in males." (PMID 37047397, 2023). "Treatment with VAS2870 ameliorated DSS-induced colitis with a reduction in DAI, MPO levels, macroscopic and histological scores, secretion of proinflammatory cytokines (TNF-α, IL-6, and IL-1β), and an increase in colon length, which were not affected by SS treatment." (PMID 37239114, 2023). "Another recent study demonstrated that in a mouse model of dextran sulfate sodium (DSS) induced colitis, the absence of dendritic HIF-1α results in enhanced severity of intestinal inflammation via increased production of pro-inflammatory cytokines IL-6 and IL-23." (PMID 34571989, 2021). "Based on our experiments, we presumed that, unlike classical IL-6-induced STAT3 activation, type I IFN-induced STAT3 might not play a protective role in DSS-induced colitis." (PMID 34349238, 2021). "Collectively, our data suggest that PKA activation is an early event in experimental colitis, and the disassociated PRKAR2A after PKA activation might take part in the subsequent STAT3 activation, but it is not dependent on the classical IL-6 signaling." (PMID 34349238, 2021). "In addition, Il-6, which is another important pro-inflammatory cytokine in IBD, decreased in the colitis + TOE group, although the difference was not significant." (PMID 33092149, 2020). "Interestingly, even rats with colitis alone, which received no midbrain injection of LPS, showed increased levels of TNF-α, iNOS, and IL-6 mRNA in the midbrain." (PMID 30441866, 2018). "Colon IL-6 production was significantly lower in n-3 and n-6 groups compared to TNBS group (P < 0.05 for both) while colon TNFα production did not significantly differ among colitis groups but tend to decrease in n-3 group compared to TNBS group (P = 0.0617)." (PMID 29670469, 2018). "The lack of IL-6 in TCR/IL-6 KO double mutant (IL-6 DKO) mice resulted in markedly reduced TNFR2 expression in colonic epithelial cells compared with TCR KO mice, even in the presence of mild colitis in both groups." (PMID 29163543, 2017). "It was observed that colitis did not interfere with the requirement of MPO activity and TNF-α levels, indicating that these inflammatory markers were not activated or deactivated and that other cytokines not investigated (IL-6 and IL-1β, e.g.)may be involved." (PMID 37577725, 2023). "When rats with experimental colitis, induced by administering 3% acetic acid intra-rectally, were treated with P. lentiscus mastic oil, administered intra-rectally, a statistically significant decrease in TNF-α level after 7 days was observed, while IL6 did not change." (PMID 37569412, 2023). "In the same study, OMVs from A. muciniphila (AmOMV) suppressed the production of IL-6 in colonic epithelial cells (CT26 cell line) stimulated with OMVs from Escherichia coli in vitro, and oral administration of AmOMV, but not viable bacteria, attenuated DSS-induced colitis in vivo." (PMID 35874661, 2022).
colitis (continued). "Moreover, treating mice with the potent semi-synthetic FXR ligand 6-Ethyl CDCA attenuated the severity of colitis and immune cell activation and the expression of various pro-inflammatory cytokines, such as TNF alpha, IL-1beta, and IL-6 in WT but not in FXR -/- mice." (PMID 35807844, 2022). "It is noteworthy that LPS-induced production of IL-12a, IL-12b, IL-23a, and IL-6 mRNA was not suppressed in colon CD11c+ DCs from Wnt5aMxΔ/Δ mice, which are consistent with the observation that Wnt5aMxΔ/Δ mice showed the phenotypes similar to control mice in DSS-induced colitis." (PMID 26030277, 2015). "Increased IL-6 expression was observed in colon tissues of DC-depleted mice, as well as a more severe colitis when exposed to dextran sodium sulfate (DSS) compared to normal mice, demonstrating that regulation of IL-6 production may contribute to DC-mediated control of intestinal inflammation." (PMID 22570785, 2012). "Thus, our data and previous findings suggest that IL-6 can finely tune the balance between negative and positive signals during DSS-induced colitis by providing protective signals to IECs or by promoting inflammation via interaction with CECs and inflammatory cells." (PMID 22962574, 2012). "Furthermore, the effect of protective construction disappeared and the expression of colonic MPO, IL-1β, IL-6, or TNF-α at the protein level was not counteracted by BD in PGF mice, indicating that the gut microbiota was essential for the effect of BD during colitis." (PMID 40745657, 2025). "From this data we conclude that the B. vulgatus triggered IL-6 secretion by LP DC in absence of proinflammatory cytokines such as IL-12 or TNF-α induces a semi-mature LP DC phenotype, which might prevent T-cell activation and thereby the induction of colitis in IL-2−/−-mice." (PMID 18545662, 2008).
rheumatoid arthritis (1,638 papers, 2005 to 2026). A chronic, systemic autoimmune disorder characterized by inflammation in the synovial membranes and articular surfaces. "Previous studies have shown that IL-6 is not only involved in the pathogenesis of rheumatoid arthritis but is also closely associated with the development of depressive symptoms." (PMID 41318430, 2025). "Diastolic dysfunction is more prevalent in patients with rheumatoid arthritis and is linked to elevated levels of circulating IL-6." (PMID 40943152, 2025). "Consistently, previous studies have found that these three metabolites are closely associated with rheumatoid arthritis, IL-6, C-reactive protein, and other inflammatory markers." (PMID 39997739, 2025). "IL-6 inhibitor therapy has been implicated in intestinal perforation in patients with rheumatoid arthritis treated with IL-6 inhibitor." (PMID 40062180, 2025). "IL-6 plays a leading role in the regulation of inflammatory responses and is implicated in the pathogenesis of chronic inflammatory diseases, including rheumatoid arthritis, inflammatory bowel disease, and cardiovascular disorders." (PMID 40571694, 2025). "In this review we have highlighted cytokines of the IL-6/IL-12 superfamily with focus on IL-6, IL-12 and IL-23 that are implicated in etiology of rheumatoid arthritis, multiple sclerosis, uveitis and Crohn’s disease." (PMID 40114923, 2025). "Deregulation of IL-6 production can cause severe disease, such as rheumatoid arthritis, psoriasis, arteriosclerosis, and cancer." (PMID 41298316, 2025). "Usage of Interleukin-6 (IL-6) blockade therapies (tocilizumab and sarilumab) achieve efficacy as therapy for rheumatoid arthritis (RA) in patients at high risk of CVD." (PMID 40064794, 2025). "IL-6-deficient mice show complete resistance in experimental models of rheumatoid arthritis and multiple sclerosis, underscoring the pivotal role of IL-6 in the development of these autoimmune diseases." (PMID 41009491, 2025). "Persistent elevation of IL-6 can promote chronic inflammation and accelerate disease-associated pathophysiology in conditions such as atherosclerosis, rheumatoid arthritis, and infection-related complications." (PMID 40497942, 2025). "Prolonged overexpression of IL-6 has been pathologically linked to multiple chronic inflammatory disorders, including rheumatoid arthritis and inflammatory bowel disease." (PMID 41019090, 2025). "Of the four subtypes of the JAK family (JAK1, JAK2, JAK3, and TYK2), JAK1 is involved in signaling through inflammatory cytokines such as IL-6, and it is known to cause lymphocyte activation and proliferation in rheumatoid arthritis (RA)." (PMID 39944226, 2025). "Some studies confirm that CLA benefits bone health by reducing inflammation and lowering IL-6 levels, which helps mitigate bone resorption and inflammation-related bone loss in conditions like rheumatoid arthritis and COPD." (PMID 40284258, 2025). "Other comorbid disorders include type 1 diabetes, associated with IL-17 and IL-6 dysregulation, and rheumatoid arthritis, typically characterized by TNF-α and IL-1β elevation." (PMID 40430113, 2025). "In rheumatoid arthritis patients, higher Si status is linked to reduced oxidative stress and lower IL-6 levels." (PMID 41470901, 2025). "Chronic inflammatory states, such as those observed in rheumatoid arthritis, inflammatory bowel disease, and systemic lupus erythematosus, are strongly associated with elevated levels of pro-inflammatory cytokines, including IL-6 and TNF-alpha." (PMID 40003660, 2025). "We performed a PubMed search using keywords such as rheumatoid arthritis, cardiovascular risk, inflammation, C-reactive protein, interleukin-6, microvascular disease, and carotid ultrasound." (PMID 41010664, 2025). "By encouraging inflammation, cytokine signaling abnormalities, like increased IL-6, are linked to rheumatoid arthritis and cytokine storms." (PMID 39996755, 2025).
rheumatoid arthritis (continued). "Tocilizumab (TCZ, which globally blocks IL-6 activities through IL-6R-α and sIL-6R), when used in treating rheumatoid arthritis, is associated with adverse cardiovascular events and an increase in serum cholesterol, which increases cardiovascular risk." (PMID 39063055, 2024). "TNF-α and IL-6 are also implicated as pathogenic factors in immune-related bone disorders, including rheumatoid arthritis and postmenopausal osteoporosis, further highlighting their pathogenic potential to bone." (PMID 39596106, 2024). "Our study also reports that Vigeo inhibited arthritis symptoms, including bone loss and serum levels of TNF-α, IL-6, and IL-1β, in a mouse model of collagen-induced arthritis/rheumatoid arthritis." (PMID 39203823, 2024). "Due to its effect on inflammatory markers such as c-peptide, estrone, total estradiol, free estradiol, leptin, CRP, IL-6, sTNF-2, and total adiponectin, caffeinated coffee consumption was linked to an increased risk of rheumatoid arthritis." (PMID 39596082, 2024). "IL-6 trans--signalling is thought to be responsible for most of the pathogenetic effects of IL-6 and is implicated in autoimmune diseases like rheumatoid arthritis and irritable bowel disease." (PMID 38442505, 2024). "Is there any association of cytokine IL-17, IL-4, IL-6, and IL-12 gene polymorphisms with disease susceptibility and severity in rheumatoid arthritis patients in the Bangladeshi population?" (PMID 38344692, 2024). "Sarilumab reduces inflammation and alleviates the symptoms associated with rheumatoid arthritis by suppressing IL-6 signaling." (PMID 38605952, 2024). "A natural substance that reduced CRP and proinflammatory, IL6 and TNFα were used as complementary therapy for managing rheumatoid arthritis, a chronic inflammatory condition associated with an increased risk of hypertension." (PMID 39558500, 2024). "Interleukin-6 (IL-6) cytokine is independently associated with higher CVD risk in patients with rheumatoid arthritis (RA)." (PMID 39596487, 2024). "Mouse models of arthritis, including antigen-induced arthritis and collagen-induced arthritis, showed IL-6 deficient mice to be completely protected against rheumatoid arthritis." (PMID 38310564, 2024). "In this case, rheumatoid arthritis (RA) patients are treated with Tocilizumab, a competitive antagonist that targets the interaction between IL-6 and a soluble variant of its receptor IL-6R (sIL-6R)." (PMID 39125692, 2024). "IL-6 trans-signalling is thought to be responsible for most of the pathogenic effects of IL-6 and is implicated in autoimmune diseases like rheumatoid arthritis." (PMID 38442505, 2024). "Extra-articular manifestations, including lung fibrosis, are common in rheumatoid arthritis, and elevated levels of IL-6 are frequently associated with the disease." (PMID 39676864, 2024). "The purpose of this work was to analyze the frequency of mutations altering the expression of IL-6 or influencing iron metabolism in patients affected by autoimmune diseases such as Rheumatoid Arthritis (RA) and Systemic Lupus Erythematosus (SLE)." (PMID 38003490, 2023). "In detail, IL-6 is a cytokine that plays a major role in the inflammatory and autoimmune processes associated with different ailments, such as rheumatoid arthritis, diabetes, Castleman’s disease, and cancer." (PMID 37629511, 2023). "Though essential to the acute phase response, prolonged IL-6-mediated recruitment of mononuclear cells has been implicated in chronic inflammatory diseases such as rheumatoid arthritis, psoriasis, and Crohn’s disease." (PMID 37682929, 2023). "IL-6 is an important proinflammatory cytokine associated with various disorders such as rheumatoid arthritis (RA), Crohn’s disease, and multiple sclerosis." (PMID 37371970, 2023).
rheumatoid arthritis (continued). "Suppressing IL-6 apparently is a good strategy to cope with dysregulated IL-6-associated diseases such as rheumatoid arthritis." (PMID 37426336, 2023). "For example, IL-6 mostly produced by macrophages in synovial fluid is implicated in rheumatoid arthritis." (PMID 37397366, 2023). "CXCL12+ fibroblasts included an inflammatory CD74hiHLAhi cluster (F-5) and a CXCL12+SFRP1+ cluster (F-6) with the highest levels of IL6, which encodes a proven drug target in rheumatoid arthritis." (PMID 37938773, 2023). "IL-6 has been implicated in an inflammatory response and development of rheumatoid arthritis, and all peptide mimics were predicted to induce IL-6 response in this study." (PMID 37513704, 2023). "Rheumatoid arthritis, in turn, has been reported to be caused by IL-6 and TNF-α secreted from M1 macrophages." (PMID 36768216, 2023). "For example, genetic predisposition to higher levels of soluble IL-6 had opposing effects on risk of rheumatoid arthritis and allergic disease." (PMID 37563310, 2023). "IL-6 is associated with various systemic conditions, includingcardiovascular disease and rheumatoid arthritis." (PMID 39077574, 2023). "Interleukin-6 plays a key role in the chronic inflammation associated with rheumatoid arthritis (RA), and blocking IL-6 signaling is an important strategy in treating RA-associated diseases clinically." (PMID 35125963, 2022). "In particular, IL-6, a pro-inflammatory cytokine implicated in the cytokine storm occurring in severe COVID-19, is upregulated in both inflammaging and Rheumatoid Arthritis (RA), a chronic autoimmune rheumatic disease." (PMID 35328795, 2022). "IL-6 is a cytokine that is involved in rheumatoid arthritis by causing bone resorption and by participating in inflammatory reactions." (PMID 35457023, 2022). "Excessive and sustained production of IL-6 is also associated with a variety of inflammatory diseases like rheumatoid arthritis, Castleman disease, systemic-onset juvenile idiopathic arthritis or cytokine releasing syndrome." (PMID 36127718, 2022). "An elevated platelet count has been associated with elevated CRP, IL-6, and erythrocyte sedimentation rate in cancer, and with IL-6 in inflammatory bowel disease and rheumatoid arthritis." (PMID 35453642, 2022). "Studies examining the effects of the IL6 polymorphism in patients with rheumatoid arthritis, which has been linked to elevated Lp(a) levels, have shown that blocking the IL6 receptor, but not TNF-α signaling, decreased Lp(a) levels by 30–40%." (PMID 35621838, 2022). "We highlight six tocilizumab responsive genes (ARID5A, BCL3, PIM1, SOCS3, BATF, MYC) that are associated with IL-6 pathway and known to be perturbed by tocilizumab treatment in rheumatoid arthritis patients." (PMID 35064122, 2022). "The first case involved a 73-year-old woman from Spain who had selective IgM deficiency, rheumatoid arthritis, fever, myalgia, headache, and bilateral conjunctivitis; she was receiving tumor necrosis-α and interleukin-6 inhibitors." (PMID 35876734, 2022). "The iNOS and COX-2 expressions are controlled by pro-inflammatory cytokines, such as TNF-α, IL-1β, and IL-6, which are implicated in numerous autoimmune and inflammatory diseases, including rheumatoid arthritis, uveitis, and sclerosis." (PMID 35877707, 2022). "For example, in rheumatoid arthritis (RA), IL-6 is produced locally in the joints, causing joint swelling and elevated C-reactive protein." (PMID 35956246, 2022). "Osteoclastic bone destruction observed in autoimmune diseases, such as rheumatoid arthritis, is caused by inflammatory cytokines, including IL-1, IL-6, TNF-α, and IL-17, which increase RANKL expression in synovial fibroblasts." (PMID 33633362, 2021). "Rheumatoid arthritis is a disease that is associated with excessive IL-6 levels; therefore, IL-6 signaling molecules were targeted in the treatment of rheumatoid arthritis." (PMID 34576053, 2021).